RN7SL760P (RNA, 7SL, cytoplasmic 760, pseudogene)
Gene: Miscellaneous RNA gene on chromosome 8 (73,833,773 to 73,834,042, reverse strand). Ensembl gene ENSG00000272469.
Homologues: Orthologues: chimpanzee Metazoa_SRP (100% identical), macaque Metazoa_SRP (80% identical), dog Metazoa_SRP (52% identical). Paralogues in human: RN7SL3 (85% identical), RN7SL1 (85% identical), RN7SL2 (84% identical), RN7SL126P (83% identical), RN7SL15P (81% identical), RN7SL664P (81% identical), RN7SL678P (81% identical), RN7SL147P (80% identical), RN7SL230P (80% identical), RN7SL448P (80% identical), RN7SL45P (80% identical), RN7SL493P (80% identical), and 704 more.